TNF (tumor necrosis factor)
Diseases named in the same sentence as TNF in open-access papers (continued):
Sharing a sentence is not in itself a finding about the gene and the disease.
tumor (continued). "Moreover, intermittent hypoxia in a solid tumor environment induced the upregulation of tumor-evasive factors, such as IL-10, HIF-1α, TGF-β1, and TNF-α." (PMID 36233088, 2022). "For instance, in a neuroendocrine tumor mouse model, targeting endothelial cells and activated tumor infiltrating macrophages (CD68+) with the LN-inducing cytokine LIGHT (TNFSF14) induces production of CCL21, TNFα, and IL1β that, overall, drive T/B cell recruitment and formation of mature TLS." (PMID 35874810, 2022). "In tumor cells, over-activated STAT3 decreases the expression of immunostimulatory factors, including pro-inflammatory cytokines (IL-12, TNF-α), IFN and chemokines (CCL5, CXCL10), while increasing the expression of certain cytokines (IL-6, TGF-β, and VEGF), thus playing an immunosuppressive effect." (PMID 36313280, 2022). "Bcl2, Bax, IL6, TNFα, CASP3, and other potential targets are related, and they may inhibit tumor growth and induce tumor cell apoptosis through AGE/RAGE and other signaling pathways." (PMID 35815259, 2022). "TNF-α and IL-17 synergistically enhance glycolysis and lactate production in CRC HT-29 cells via activation of the NF-κB axis in tumor cells, and they promote GLUT1 and hexokinase 2 (HK2), as well as expression of the common target genes HIF-1α and c-myc which, in turn, promote tumorigenesis." (PMID 36588722, 2022). "Tumor cell lysis can also induce the production and secretion of inflammatory mediators, including type I interferons (IFNs), interferon-gamma (IFN-γ), interleukin-12 (IL-12), and tumor necrosis factor-α (TNF-α)." (PMID 35295845, 2022). "Furthermore, when examined by qPCR, we found that the expression of immune-promoting cytokines (TNF-α, IL-1β and IFN-γ) in SU4312-treated tumor tissues was significantly higher than that in the control group." (PMID 36013004, 2022). "Similarly, the intervention decreased circulating tumor-promoting growth factors and inflammatory cytokines (i.e., BDNF, TNFα, FGF-2), with greater effects in obese compared to lean rats." (PMID 35725493, 2022). "Notably, EVs derived from γδ T cells, a unique population of T cells sensing target antigens in an MHC-independent way, express NKG2D, FasL, TNFα, IFN-γ and perforin on their membrane surface and are able to significantly reduce tumor growth." (PMID 35927755, 2022). "Tumor necrosis factor alpha (TNF alpha) can activate the release of VEGF from neutrophils and, in this way, increase the vascular permeability and supply to malignant tissue promoting tumor growth and metastasis." (PMID 36556990, 2022). "Although to lesser degree, TNF-α and IFN-γ blockade also accelerated tumor growth in WT mice." (PMID 36467403, 2022). "We detected upregulated levels of cytokines such as IFNγ (unpaired t-test, p < 0.0001) and TNFα (unpaired t-test, p = 0.0003), which could favor the increase in infiltrating CD8+ T cells observed in the tumor regions of Sftpc-KO mice." (PMID 35326737, 2022). "Moreover, we found that IgG control treatment in tumor model resulted in decreased number of CD4+ and CD8+ T-bet+TNF-α+ T cells which were induced by the anti-IL-9 antibody treatment." (PMID 35514957, 2022). "Consequently, Whsc1 deletion impeded T cell–mediated tumor cell–killing efficiency and produced less IFN-γ and TNF-α." (PMID 35230972, 2022). "In both serum and the supernatants, the levels of IFN-γ and TNF-α were strikingly up-regulated after Nr-CWS treatment, suggesting that Nr-CWS could enhance anti-tumor activities of NK cells through regulating cytokines production." (PMID 36110249, 2022). "In mice treated with Imprime, a significantly higher percentage of CD8 T cells expressed both Ki67 and GrzB, and when isolated and stimulated with anti-CD3/CD28 monoclonal Abs, exhibited enhanced proliferation and production of critical anti-tumor effector cytokines IFN-γ, IL-2, and TNF-α." (PMID 35692755, 2022).
tumor (continued). "The exhausted tumour-specific T-cells do not express characteristic pro-inflammatory cytokines such as IL-2, TNFα, and IFNγ, but instead produce the inhibitory receptors such as programmed death 1 (PD-1) and cytotoxic T-lymphocyte associated protein 4 (CTLA4)." (PMID 36140243, 2022). "It was also proposed that TNF-α-induced TNFR2 expression triggers the proliferation of CRC cells and intestinal epithelial cells by stimulating the signal transducer and activator of transcription-3 (STAT3) protein for tumor promotion." (PMID 35954156, 2022). "Moreover, the tumor specimens were all stained by immunohistochemistry to show the expression of DGCR8, SPI1, TNF-α, nestin, and Ki-67." (PMID 35945192, 2022). "Interestingly, TNF-α is mainly released from macrophages, and TNF-α can directly lead to tumor promotion or the apoptosis of tumor cells." (PMID 34663798, 2021). "Under tumor conditions, various cytokines, such as GM-CSF, IL6, TNF-α, and other chemokines." (PMID 34479503, 2021). "The secretion profile of some of the cytokines related to inflammation in addition to tumor invasion, progression, and migration, namely, IFN-γ, TNF-α, IL-1β, IL-6, IL-8, and IL-12, demonstrated a decrease in values following treatment with the hWJSC-CC, hWJSC-CM (100%), and hWJSC-L (15 μg/ml)." (PMID 33869169, 2021). "Of the cells isolated from MC38 tumors, the bystander memory cells showed superior cytokine production to the tumor-specific T cells and contained on average 3.7-fold more IFN-γ+ TNFα+ cells, and nearly 9-fold more IFN-γ+ IL-2+ cells than tumor-specific T cells." (PMID 34867942, 2021). "Notably, immunomodulatory cytokines secreted by CAFs, such as IL-10, tumor necrosis factor (TNF), and interferon γ, are reported to be involved in the regulation of tumor cell immune responses by recruiting and polarizing macrophages." (PMID 35058933, 2021). "Upon recognition of the antigen, the expanded T cells produced IFNγ and TNFα and specifically killed antigen-positive cells in vitro with high efficacy, sparing antigen-negative tumor cells." (PMID 33796916, 2021). "Furthermore, dendritic cells exposed to MUC2 produce less TNFα and IL-12, as well as more IL-10 and TGFβ1 in the large intestine, which suggests that MUC2 can deliver immunoregulatory signals to support tumor growth and treatment resistance." (PMID 34300195, 2021). "In vitro exposure of unpolarized (M0) bone-marrow-derived macrophages (BMDM) from control EMT6 tumor-bearing mice to IFNγ and TNFα induced significant M1 but not M2 polarization." (PMID 34446712, 2021). "While TREM-1 engagement enhanced TNF, a TREM-2 ligand was detected on MDSC and TAM, suggesting that both TREM could be functional in the tumor setting." (PMID 35223446, 2021). "However, the researches in breast cancer indicated that E2 reverses the anti-tumor effect of TNF-α by inhibiting NF-κB and further inactivating IAP, which blocks the process of tumor cells apoptosis." (PMID 34098945, 2021). "Furthermore, the recruitment of immune cells to tumor sites and the number of CD8+ T cells increased in mouse spleens, along with increased upregulation of TNF-α and IL-6." (PMID 34575449, 2021). "A similar concept incorporated a mutated TNF or IFN-γ with decreased affinity for its receptor and showed target-specific cytotoxicity, induced cellular adhesion molecules in the tumor, and did not increase toxicity." (PMID 33803078, 2021). "In contrast, N1 TANs produce chemokines, such as C-C motif chemokine ligand 3 (CCL3, CXCL9, CXCL10), to recruit CD8+ T cells to TME and secrete cytokines (e.g., IL-12, TNF-α, and GM-CSF) to activatethe cytotoxicity of CD8+ T cells, thus providing anti-tumor effect." (PMID 34359674, 2021). "Tumor‐derived tumor necrosis factor‐α (TNF‐α) promoted neutrophil activation and neutrophil B7‐H2 expression through ERK‐NF‐κB pathway, and a significant correlation was found between the levels of TNF‐α and CD54+ or B7‐H2+ neutrophils in tumor tissues." (PMID 34185422, 2021).
tumor (continued). "In the tumor microenvironment, PD-1 expression is sustained highly on exhausted T cells, followed by the diminished production of effector factors, including interferon-gamma (IFN-γ), interleukin-2 (IL-2), and tumor necrosis factor-alpha (TNF-α)." (PMID 34819055, 2021). "Evidence from many basic experiments indicates that some mediators contained in mast cells, such as TNF-α, prostaglandins, VEGF, tryptase, and chymase, seem to be important in promoting tumor hyperplasia and invasive and metastatic processes, as well as creating the TME." (PMID 34884420, 2021). "It has been reported that IL-10 produced by MDSCs could decrease the secretion of IL-6, IL-12, and tumor necrosis factor-α (TNF-α) of macrophages, which remarkably suppress their anti-tumor activity." (PMID 35004667, 2021). "Tumor markers (CEA, CYFRA 21-1, and NSE) were measured in the patients’ sera and plasmas, along with IL-6, TNF-α, SAA1, CRP, MMP-2, MMP-9, glucose, lactate, and LDH, utilizing enzyme-linked immunosorbent assays, enzyme immunoassays, and automated clinical chemistry and turbidimetry systems." (PMID 34439874, 2021). "Tumor necrosis factor-α is a member of the cytokine family, which can induce apoptosis of tumor cells and coordinate non-specific immune response, which is produced in the early stage of inflammatory response." (PMID 34925074, 2021). "Infusing Perforin-/- CD137L/IL-15/IL-15Rα activated NK cells had no impact on GVT, whereas TNF-α-/- CD137L/IL-15/IL-15Rα activated NK cells improved GVT by decreasing peripheral effector cell subsets while preserving tumor-infiltrating lymphocytes." (PMID 34489927, 2021). "Tumor necrosis factor-α (TNFα) is another cytokine secreted at high levels in the TME during the early stages of tumorigenesis that has an established role in chronic inflammation, angiogenesis, tissue remodeling, tumor growth, and metastasis." (PMID 34360868, 2021). "This is in contrast to the rapid and complete degradation of c-IAP1 by c-IAP1 antagonists and activation of TWEAK-FN14 signaling, respectively, which both induce apoptosis but not necroptosis of tumor cell lines by NF-κB-dependent autocrine TNF-production." (PMID 33712742, 2021). "CAFs with high expression of podoplanin can also secrete a large number of cytokines and chemokines, such as TGF-β, tumor necrosis factor-α (TNF-α), interleukin-8 (IL-8), vascular endothelial growth factor (VEGF), which may promote tumor progression." (PMID 34566887, 2021). "MSCs could sense cancer as a damaged tissue thereby migrating towards it in response to tumor-derived inflammatory molecules, such as SDF-1, TNF-a and interleukins IL-6 and LL-37." (PMID 35111750, 2021). "TNF-α induced the expression of adhesion molecules such as intracellular adhesion molecule (ICAM)-1, E-selectin, and VCAM-1 in liver sinusoidal endothelial cells and induced tumor metastasis." (PMID 33986746, 2021). "This study, although it does not demonstrate that TNF-α/Egr is derived from the tumor tissue, constitutes an interesting proof of principle." (PMID 34831432, 2021). "Serum TNF-α levels may have potential value in the follow-up of tumor patients during PBM treatment and a decrease in TNF-α may be indicative of a better clinical response." (PMID 33572840, 2021). "Lidocaine and ropivacaine, for example, inhibited TNF-α-induced Src activation independent of sodium channel blockade in non-small cell lung cancer cells in vitro, thus also reducing tumor cell migration." (PMID 33670434, 2021). "In addition to Teffs, tumor-infiltrating CD8+ Trm T cells also exhibit anti-tumor activity by releasing lytic granules, granzyme B (GzmB), IFN-γ, and tumor necrosis factor (TNF)-α." (PMID 34742349, 2021). "This may be due to tumor cells affected the activation of NK cells by inhibiting IL-2, IFN-γ, and TNF-α secretion, thus rendering them inept." (PMID 35046996, 2021).
tumor (continued). "TAMs initiate a tumor-promoting microenvironment and may cause tumor evasion from immune destruction by elaborating various cytokines (e.g., IL1, IL6, TNF-α) and growth factors (e.g., TGF-β) that reduce T-cell activity and T cell-mediated tumor elimination." (PMID 34577857, 2021). "Furthermore, MUC1-specific CAR-T cells significantly increased secretion ofIL-2 (597.5 ± 38.89 pg/mL, 15-fold), TNF alpha(359 ± 1.41 pg/mL, 6-fold) and IFN-γ (182 ± 9.89pg/mL, 9-fold) in response to MCF-7, anotherMUC1 positive tumour cell line." (PMID 32347044, 2021). "SPARC deletion promoted ROS generation and increased the production of pro-inflammatory and pro-angiogenic cytokines IL-6, CCL2, VEGF, and TNF-α as well as cytokines with pro-migratory ability, CCL3, CXCL2, CSF-1, and M-CSF, accompanied by greater tumor infiltration by mac1-positive TAMs." (PMID 34209679, 2021). "This anti-tumor effect was related to the downregulation of ERα, PRα&β, and TRPV1 expression, maintenance of immune function, especially by preserving NK cell activity, and reduced production of proinflammatory cytokines such as TNF-α and IL-6." (PMID 34764420, 2021). "Tregs express immunoregulatory molecules (PDL1 and CTLA4) and produce immunosuppressive cytokines (IL-10, IL-35, TGF-β), which inhibit the synthesis of TNF-α, IFN-γ and IL-17 in Th1 and Th17 cells and reduce the production of perforin and granzymes in CTLs, alleviating their anti-tumor properties." (PMID 34830312, 2021). "M2 macrophages secrete pro-tumorigenic, pro-angiogenic, and immunosuppressive factors such as IL10, TGFβ, and VEGFA; whereas M1 macrophages produce pro-inflammatory cytokines such as TNFα, IL1, IL12, and IFNγ, and reactive oxygen species, which prevent tumor growth." (PMID 34517894, 2021). "In TNF induced NF-κB activation, quinone oxidoreductase 1 (NQO1) plays a pivotal role in activation of NF-κB signaling, and inhibition of NQO1 activity hampers the proliferation, survival, invasion, and metastasis of tumor cells." (PMID 33526051, 2021). "The anti-tumor “N1” phenotype exhibited increased tumor cytotoxicity, elevated expression of CXCL13, CCL3, CCL6, CXCL10, TNFα and ICAM-1 and low ARG1 content, while the pro-tumor “N2” neutrophils expressed high levels of ARG1, MMP9, VEGF and several cytokines, including CCL2, CCL5, CCL17 and CXCL4." (PMID 34572138, 2021). "However, it has also been shown that activated eosinophils enhanced tumour rejection in the presence of tumour-specific CD8+ T cells, through action to alter the TME with increased IFN-γ and TNF and to induce tumour vascular normalisation." (PMID 33917287, 2021). "It is credible that monocytes should accumulate in the infected tumor as these cells have been shown to accumulate in inflamed tissues and provide inflammatory cytokines, such as TNF‐α, which would not be conducive to tumor progression [23, 24‐26]." (PMID 34633664, 2021). "Moreover, a "NSCLC-pathway" containing TNF, PI3K-Akt and VEGF signaling pathways was assembled and separated into two represent therapeutic modules (immunization module and tumor related module)." (PMID 33460401, 2021). "Surprisingly, lymphotoxin alpha (LTA), and not TNF, secreted by the tumor cells, was critical for the extravasation." (PMID 33546280, 2021). "Cytotoxic lymphocytes and NK cells also induce death ligands, (tumor necrosis factor, TNF; Fas ligand, FasL, and TNF-related apoptosis-inducing ligand, TRAIL) to eliminate tumor cells through the activation of their specific receptors present on the tumor cells." (PMID 33807260, 2021). "In cultured LLC cells and MMTV-PyMT tumour cells, AKTi addition led to a reduction of cell viability by 37% and 35%, respectively, regardless of the inclusion of TNFα and/or IFNγ." (PMID 34285232, 2021). "Importantly, TNF-α and IFN-γ synergistically induced signaling in CD4+ T cells that prevents immune evasion, tumor cell proliferation, and multistage carcinogenesis." (PMID 33957948, 2021).
tumor (continued). "For the T-P network, we found that about 22% of targets were involved in TNF, PI3K-Akt and VEGF signaling pathway, while P-D chord diagram showed that TNF, PI3K-Akt and VEGF signaling pathways were significantly enriched in Cancer and Neoplasm Metastasis diseases." (PMID 33460401, 2021). "Overall, as only TILs with high level of recognition were used, the mean percentage of “bulk” TILs that were reactive to autologous tumor cells was high (measured with upregulation of CD137, TNF, IFNγ or CD107a: 41% in CD8+ TILs, n=21; and 29% in CD4+ TILs, n=16." (PMID 34707600, 2021). "Furthermore, up-regulated CD276 promotes immune escaping of tumor cells, reducing the secretion of IFN-γ, tumor necrosis factor-alpha (TNF-α), and other cytokines." (PMID 33842369, 2021). "We also confirmed that Vγ9Vδ2 T cells treated with the IDO inhibitor promoted perforin production, but not IFN-γ and TNF-α under the tumor stress." (PMID 34381711, 2021). "As macrophages (defined as CD14+CD11b+) constitute a major TNF-producing cell subpopulation and were the dominant CD16+ cell subset in the CRC tumor suspensions, the observed increase in TNF levels could be macrophage-derived." (PMID 34771609, 2021). "In sharp contrast, these mice still displayed extreme sensitivity to DMBA/TPA-induced tumor formation, indicating that, in this case, dysregulated production of TNF in the absence of TTP in epidermal cells is not the primary driver." (PMID 33497366, 2021). "Radiation also results in upregulation of IL-1β, TNF-α and type I and II interferons, and these induce expression of cell adhesion molecules e.g., VCAM-1 and ICAM-1 on endothelial cells, promoting migration of lymphocytes into the tumor parenchyma." (PMID 34439387, 2021). "It was later shown that tumor cells transfer cGAMP to astrocytes through these gap junctions, resulting in astrocyte cGAS-STING-mediated IRF activation, and subsequent secretion of tumor-supportive IFN-α, TNF, and TGF-α." (PMID 34716900, 2021). "In addition, parthenolide has been shown to greatly sensitise a variety of tumour cells, including NPC to TNF-α-induced apoptosis by preventing constitutive activation of NF-κB in tumour cells." (PMID 33918087, 2021). "In contrast, TRM-like cells found in endometrial and breast cancer retained equal capacities to produce IFN-γ, TNF-α and IL-2, compared with tumor-infiltrating T cells that did not display a TRM phenotype." (PMID 34571883, 2021). "Moreover, their findings showed that the deprivation of methionine promoted CD8+ T cell apoptosis and reduced its IFNγ and TNFα production, whereas methionine supplement improved tumor-infiltrating CD8+ T cell cytokines production and anti-tumor responses." (PMID 35087832, 2021). "High salt treatment enhanced the secretion of inflammatory cytokines (IFNγ, TNFα and IL-17) from DLNs, tumor splenocytes and non-tumor splenocytes, as compared to respective equimolar mannitol treatment." (PMID 33918403, 2021). "Besides, the higher level of TNF-α and IFN-γ in serum and tumor tissues of combination therapy indicated that NPPA-PTX NPs induced NK cell proliferation, and stimulated TNF-α and IFN-γ production." (PMID 33866918, 2021). "Tumor-infiltrating T cells from KO mice produced significantly more IFN-γ and TNF-α." (PMID 34283809, 2021). "Furthermore, tumor‐derived GDF‐15 inhibits the synthesis of nitric oxide and TNF‐α through TGF‐activated kinase‐1 in macrophages." (PMID 33738380, 2021). "High levels of TNF-α and IFN-γ expression were observed in the tumor tissues." (PMID 33406722, 2021). "For preclinical in vivo evaluation of TNF-based products, although murine TNF is usually used as a surrogate molecule, the human payload can also be employed as it cross-reacts with the murine TNFR1 and triggers killing of mouse tumor cells." (PMID 34576184, 2021).